FDX1 (ferredoxin 1)
Description:
Essential for the synthesis of various steroid hormones. Participates in the reduction of mitochondrial cytochrome P450 for steroidogenesis. Transfers electrons from adrenodoxin reductase to CYP11A1, a cytochrome P450 that catalyzes cholesterol side-chain cleavage. Does not form a ternary complex with adrenodoxin reductase and CYP11A1 but shuttles between the two enzymes to transfer electrons (By similarity).
Synonyms: ADX; FDX; LOH11CR1D
Tractability: Small molecule: a structure with a bound ligand is known. PROTAC: its protein half-life has been measured.
Gene: Protein-coding gene on chromosome 11 (110,429,379 to 110,464,884, forward strand). Ensembl gene ENSG00000137714.
Subcellular location: Mitochondrion matrix
Subcellular location (Human Protein Atlas): Mitochondria
Pathways (Reactome):
Metabolism: Electron transport from NADPH to Ferredoxin; Endogenous sterols; Mitochondrial iron-sulfur cluster biogenesis; Pregnenolone biosynthesis
Disease: Defective CYP11A1 causes AICSR
Metabolism of proteins: Protein lipoylation
Gene Ontology:
Molecular function: 2 iron, 2 sulfur cluster binding; electron transfer activity; iron ion binding; iron-sulfur cluster binding
Biological process: cholesterol metabolic process; hormone biosynthetic process; P450-containing electron transport chain
Cellular component: mitochondrion; mitochondrial matrix
Genetic constraint (gnomAD): Loss-of-function variants: 5 observed, 8.1 expected, observed/expected ratio (o/e) 0.62, 90% interval 0.32 to 1.29. That is too few expected variants to judge how well the gene tolerates losing a copy. Missense variants: 140 observed, 132.2 expected, observed/expected ratio (o/e) 1.06, 90% interval 0.92 to 1.22. Synonymous variants: 65 observed, 60.26 expected, observed/expected ratio (o/e) 1.08, 90% interval 0.88 to 1.33.
Homologues: Orthologues: chimpanzee FDX1 (99% identical), macaque FDX1 (97% identical), pig FDX1 (79% identical), mouse Fdx1 (77% identical), rat Fdx1 (66% identical), guinea pig FDX1 (62% identical), dog FDX1 (62% identical), tropical clawed frog fdx1 (60% identical). Paralogues in human: FDX2 (28% identical).
Diseases named in the same sentence as FDX1 in open-access papers:
FDX1 is named in the same sentence as 141 diseases in open-access papers, as found by Europe PMC text mining. Sharing a sentence is not in itself a finding about the gene and the disease. The quoted sentences say what the papers report.
lung adenocarcinoma (34 papers, 2021 to 2025). A carcinoma that arises from the lung and is characterized by the presence of malignant glandular epithelial cells. "In lung adenocarcinoma, FDX1 was a part of the electron transport chain risk signature predicting prognosis and was a regulator of glucose metabolism, fatty acid oxidation, and amino acid metabolism." (PMID 36825202, 2023). "Consistent with our study, the decreased expression of FDX1 was associated with a poor survival outcome in lung adenocarcinoma." (PMID 36092887, 2022). "It was noted in the latest articles that FDX1 is firmly associated with the metabolism of the three major nutrients (glucose, fatty acids, and amino acids) in lung adenocarcinoma and its down-regulated expression could be an indicator of poor prognosis." (PMID 36212447, 2022). "It directly targets FDX1 and inhibits FDX1-mediated Fe-S cluster biosynthesis, thereby inducing copper-dependent cell death in human breast cancer and lung adenocarcinoma cells." (PMID 40244269, 2025). "Collectively, these aspects warrant further investigation and discussion in the context of our research on Ferredoxin 1 and its implications in lung adenocarcinoma progression." (PMID 38802900, 2024). "Downregulation of FDX1 significantly changes glucose, amino acid, and fatty acid oxidative metabolism in lung adenocarcinoma." (PMID 36925927, 2023). "Evidence suggests that knockdown of FDX1 affects glucose metabolism and fatty acid oxidation in lung adenocarcinomas." (PMID 37301546, 2023). "FDX1 impacted the prognosis of lung adenocarcinoma and was closely related to glucose metabolism, fatty acid oxidation and amino acid metabolism." (PMID 36895378, 2023). "As for lung adenocarcinoma, FDX1 promotes production of ATP in tumor cells and is closely associated with glucose metabolism, fatty acid oxidation, and amino acid metabolism." (PMID 36173462, 2023). "A study has studied the crucial role of cuproptosis-related genes (CRGs) in lung adenocarcinoma and found that MTF1, SLC31A1, FDX1 and DLD were associated with the tumor microenvironment and immune responses in lung adenocarcinoma." (PMID 37380924, 2023). "In tumor studies, FDX1 has been found to affect prognosis and mediate glucose metabolism, fatty acid oxidation and amino acid metabolism in lung adenocarcinoma, as well as to influence alterations in major pathways in renal cell carcinoma." (PMID 37405988, 2023). "Studies have shown that FDX1 can impact the prognosis and mediate the metabolism of lung adenocarcinoma." (PMID 36915038, 2023). "We also found that PDHB and DLD were differentially expressed in colorectal cancer, while FDX1 was distinctly expressed in lung adenocarcinoma." (PMID 36506302, 2022). "Limited findings on lung adenocarcinoma suggest that the function of FDX1 in tumourigenesis is related to the metabolism of glucose, amino acids, and fatty acid oxidation." (PMID 36186457, 2022). "For instance, elesclomol (ES) directly targets FDX1 and inhibits FDX1-mediated Fe-S cluster biosynthesis, thereby promoting copper-dependent cell death in human breast cancer and lung adenocarcinoma cells." (PMID 36210836, 2022). "For example, in lung adenocarcinoma, FDX1 has been reported to be closely involved in fatty acid oxidation, glucose, and amino acid metabolism." (PMID 36333684, 2022). "Elesclomol directly targets FDX1 in human breast cancer and lung adenocarcinoma cells, inhibits FDX1-mediated Fe-S cluster biosynthesis, and promotes copper-dependent cell death." (PMID 36210836, 2022). "Given the central role of Ferredoxin 1 as a signaling mediator in lung adenocarcinoma tumorigenesis, it is plausible that it may also contribute to KRAS G12C resistance." (PMID 38802900, 2024). "FDX1 may affect the prognosis and regulate the metabolism of lung adenocarcinoma and is highly expressed in GBM and UCEC but lowly expressed in 12 other types of cancer." (PMID 38573998, 2024).
lung adenocarcinoma (continued). "Although there is no direct evidence that mitotane mediates the treatment of NSCLC, experiments have shown that its target, FDX1, could mediate the metabolism of lung adenocarcinoma and affected prognosis." (PMID 36768566, 2023). "Meanwhile, the prognosis of lung adenocarcinoma patients with low expression of FDX1 is even worse." (PMID 36925927, 2023). "Moreover, FDX1 is highly expressed in human malignant melanoma cells, osteoblastic osteosarcoma tissues, and lung adenocarcinoma cells." (PMID 36210836, 2022). "A study found that FDX1 can impact the prognosis of lung adenocarcinoma." (PMID 36247012, 2022). "FDX1 was revealed to impact the prognosis and mediate the metabolism of lung adenocarcinoma." (PMID 36531021, 2022). "By systematically analyzing the genetic alterations of 10 cuproptosis-related genes in lung adenocarcinoma, we found that CDKN2A, DLAT, LIAS, PDHA1, FDX1, GLS, and MTF1 were differentially expressed between lung cancer tissues and adjacent tissues." (PMID 36712848, 2022). "Studies conducted with siRNA knockdown of FDX1 in lung adenocarcinoma reported that neither tumour proliferation inhibition nor apoptosis or cell cycle arrest were induced." (PMID 36186457, 2022). "Mechanistically, knockdown of FDX1 mainly affected the energy metabolism, whose reprogramming is a characteristic of carcinoma, but showed no apparent effect on cell proliferation and apoptosis in lung adenocarcinoma cells." (PMID 36092887, 2022). "In lung adenocarcinoma (LUAD), FDX1 knockdown did not inhibit tumor cell growth or induce apoptosis or abnormal cell cycle distribution." (PMID 37193786, 2023).
hepatocellular carcinoma (26 papers, 2022 to 2026). A malignant tumor that arises from hepatocytes. "One of the important regulators, FDX1, has been demonstrated to be substantially downregulated in hepatocellular carcinoma (HCC), higher expression of this gene is associated with a longer survival period." (PMID 39036924, 2024). "In hepatocellular carcinoma, the downregulation of FDX1 contributes to metabolic reprogramming, leading to reactive oxygen species-mediated mitochondrial autophagy and activation of the PI3K/AKT signaling pathway, resulting in poor prognosis." (PMID 40276654, 2025). "Decreased FDX1 expression has been reported to promote the progression of hepatocellular carcinoma and activate the PI3K/AKT pathway." (PMID 40244269, 2025). "Previous studies have shown that FDX1, as a key gene in cuproptosis, is involved in the progression of hepatocellular carcinoma and glioma as well as tumor immunity and drug sensitivity." (PMID 38200479, 2024). "The FDX1 phosphorylation at the S177 locus in hepatocellular cancer functioned in the role of cellular signal transduction, and some publications supported this result." (PMID 37298135, 2023). "In hepatocellular carcinoma, FDX1 was considerably downregulated, and high expression was linked to a prolonged survival time." (PMID 36454396, 2022). "Similarly, integrated metabolomic–transcriptomic analyses have linked cuproptosis-associated genes (FDX1, DLAT, LIAS) with immunotherapy outcomes in cancers such as melanoma, lung cancer, and hepatocellular carcinoma." (PMID 41562065, 2025). "Similarly, integrated transcriptomic–metabolomic analyses have uncovered cuproptosis-associated gene networks (e.g., FDX1, DLAT, LIAS) that correlate with immunotherapy outcomes in melanoma, lung cancer, and hepatocellular carcinoma." (PMID 41562065, 2025). "Additionally, the ferroptosis inducers sorafenib and erastin promote cuproptosis in primary hepatocellular carcinoma by inhibiting FDX1 protein degradation via inhibition of cystine transport and by decreasing synthesis of the intracellular copper chelator GSH." (PMID 40276654, 2025). "For example, individuals with hepatocellular carcinoma (HCC) had significantly reduced levels of the critical cuproptosis regulator FDX1, making HCC cells resistant to cuproptosis." (PMID 39620145, 2024). "In this study, a 365-liver hepatocellular carcinoma (LIHC) cohort from the TCGA dataset and a retrospective HCC cohort from Zhuhai People’s Hospital were enrolled to explore effect of FDX1 expression on patient survival with HCC." (PMID 37361595, 2023). "constructed a prognostic model of HCC using the expression levels of ferredoxin 1 (FDX1) in hepatocellular carcinoma (HCC)." (PMID 36341437, 2022). "Recent studies have emphasized the pivotal function of FDX1 across various cancer types, including clear cell renal cell carcinoma (ccRCC), hepatocellular carcinoma (HCC), and gliomas, where its expression levels have been associated with patient survival outcomes." (PMID 40589743, 2025). "Additionally, sorafenib and erastin, known inducers of ferroptosis, were found to inhibit FDX1 degradation, enhance the aggregation of copper‐dependent lipoylated proteins, and stimulate cuproptosis in primary hepatocellular carcinoma (HCC) cells." (PMID 39290254, 2024). "Compared to paired normal tissues, FDX1 expression levels were upregulated in glioblastoma (GBM) and female genital tumors, and downregulated in solid tumors like lung adenocarcinoma (LUAD) and hepatocellular carcinoma (HCC)." (PMID 36882769, 2023).
glioma (23 papers, 2022 to 2025). A benign or malignant brain and spinal cord tumor that arises from glial cells (astrocytes, oligodendrocytes, ependymal cells). "The present study investigates the prognostic value of the FDX1 gene and its association with immune infiltration in gliomas." (PMID 37301546, 2023). "OS results showed that expression of FDX1 was risk factor in glioma (GBMLGG) (HR = 4.17, p = 1.7e-19), LGG (HR = 2.92, p = 9.5e-6), and was protective factor in KIRC (HR = 0.48, p = 1.3e-8) and pan-kidney cohort (KIPAN) (HR = 0.59, p = 8.1e-8)." (PMID 36825202, 2023). "The results provided valuable insight into the mechanisms involved in the association between FDX1 and cancer-immune interactions in glioma." (PMID 37301546, 2023). "In different grades, our results illustrated high expression of FDX1 as a risk factor for WHO II primary glioma (LGG) (p = 0.018), and the result was similar to TCGA-LGG." (PMID 36825202, 2023). "Kaplan-Meier analysis demonstrated that high FDX1 expression was associated with poor prognosis in glioma." (PMID 37301546, 2023). "The results showed that high expression of FDX1 was significantly associated with the prognosis time of all glioma patients." (PMID 36523779, 2022). "The innovation of this study is that, for the first time, we found that FDX1 in glioma is associated with poor patient prognosis, and also explored the possible mechanism of FDX1 in glioma involved in the immune microenvironment." (PMID 36523779, 2022). "At the same time, we verified the result in three independent cohorts of CGGA, and the conclusion indicate that high expression of FDX1 gene was associated with the overall prognosis of glioma." (PMID 36523779, 2022). "Using univariate Cox analysis, we previously validated that FDX1 was a risk factor for gliomas." (PMID 37515314, 2023). "FDX1 is found to be highly expressed in gliomas and associated with worse prognosis." (PMID 37564178, 2023). "Association of FDX1 expression and clinicopathological parameters in patients with gliomas." (PMID 36579333, 2022). "further highlighted that the FDX1 expression is promoted by the c-Myc-YTHDF1 signaling pathway in glioma cells and demonstrated that the c-Myc-YTHDF1/FDX1 axis inhibited the mitophagy and promoted the malignant phenotype of glioma cells." (PMID 38918694, 2024). "Another example is the increased expression of the gene for the copper reductase ferredoxin 1 (FDX1) in gliomas compared to healthy tissue, which correlates significantly with a poorer prognosis for patients." (PMID 39062119, 2024). "Several gene expression analyses independently confirmed increased expression of the FDX1 gene in gliomas compared to healthy tissue, and this expression correlated significantly with a poorer clinical prognosis." (PMID 39062119, 2024). "This prediction of poorer prognosis was also independently confirmed for high-grade gliomas and for low-grade gliomas, while in renal cell carcinomas, the opposite result was confirmed and FDX1 expression correlated with a better prognosis." (PMID 39062119, 2024). "The transwell assay further showed that FDX1 silencing inhibited the invasion and migration ability of glioma cells." (PMID 37301546, 2023). "FDX1 was highly expressed in IDH wildtype 1p/19 non-codeletion patients, suggesting a differential FDX1 expression in glioma molecular subtypes and the value of survival and drug sensitivity prediction of FDX1." (PMID 36825202, 2023). "Patients with glioma having high- and low-FDX1 expression showed differential immunotherapy response." (PMID 37301546, 2023). "Survival analysis revealed FDX1 predicted poor prognosis in glioma (GBMLGG), brain lower-grade glioma (LGG), and good prognosis in the pan-kidney cohort (KIPAN), and kidney renal clear cell carcinoma (KIRC)." (PMID 36825202, 2023).
glioma (continued). "To explore the roles of FDX1 in glioma, we evaluated the correlation between FDX1 expression and copy number variations; we found that copy number variations mainly included diploidy, gain and shallow deletions, and small amplification ratios." (PMID 37301546, 2023). "The scratch assay indicated a decrease in the migration ability of glioma cells after FDX1 silencing." (PMID 37301546, 2023). "Then, the survival analysis displayed a high expression of FDX1 was a poor prognostic factor for all WHO grade survival in primary glioma (p < 0.0001) or recurrent glioma (p = 0.034)." (PMID 36825202, 2023). "Only GLS and ATP7B had low expression levels in glioma patients; however, others, including FDX1, LIPT1, DLD, and SLC31A1, were overexpressed." (PMID 37515314, 2023). "We note that, FDX1 showed a strong positive correlation with the poor prognosis and pathological grade of glioma." (PMID 36915038, 2023). "In summary, we explored the possible prognostic value of CRGs in glioma, and explored the possible regulatory mechanism of miR-606 on FDX1, these results provide a novel insight into comprehensive glioma treatment." (PMID 36915038, 2023). "As for survival analysis, the high expression of FDX1 and SLC31A1 protein was associated with poor survival in glioma patients (p < 0.05 for FDX1 and p < 0.001 for SLC31A1)." (PMID 36856182, 2023). "Two or more alterations of FDX1 were detected in different subtypes of glioma; notably, amplification alterations were more common in glioma samples." (PMID 37301546, 2023). "The regulation of FDX1 in glioma cells was also studied; in vitro experiments confirmed that the invasive and metastatic abilities of the glioma cells were apparently suppressed after FDX1 knockdown." (PMID 37301546, 2023). "We also studied the relationship between FDX1 and immune related scores in glioma patients to explore potential immunotherapy options." (PMID 37301546, 2023). "And the mRNA and protein levels of FDX1 were significantly increased in glioma tissues and cells, knockdown of FDX1 significantly inhibit aerobic glycolysis and proliferation of GBM cells." (PMID 36915038, 2023). "We further examined the methylation level of FDX1 in glioma and found that the promoter of FDX1 showed low methylation levels." (PMID 37301546, 2023). "Multivariate Cox regression indicated that FDX1 was an independent prognostic factor for patients with glioma." (PMID 37301546, 2023). "Considering that FDX1 is a key regulator mediating cuproptosis, our study also provided a new perspective and direction for the future research on the treatment of glioma using the cuproptosis mechanism." (PMID 36856182, 2023). "In this study, survival analysis showed that upregulation of FDX1 expression is predictive of a poor prognosis in glioma." (PMID 37301546, 2023). "In the present study, we investigated the expression and prognostic value of the FDX1 gene in gliomas by performing database analyses and constructing Kaplan-Meier curves." (PMID 37301546, 2023). "Specially, we found FDX1 was a poor prognosis predictor and correlated to the suppressive immune microenvironment in lower-grade gliomas with the validation of CGGA." (PMID 36825202, 2023). "We performed experiments in vitro to explore the FDX1-mediated mechanisms in glioma progression and validate the effect of FDX1." (PMID 37301546, 2023). "Multivariate Cox regression indicated that FDX1 expression (HR=1.771, p=0.005) was an independent prognostic factor for glioma in the TCGA cohort." (PMID 37301546, 2023). "The scratch and transwell assays showed that active NOD1 in FDX1-silenced glioma cells increased invasion and migration ability." (PMID 37301546, 2023). "Multivariate Cox regression showed that FDX1 expression (HR=1.945, p=0.002) was an independent prognostic indicator for glioma; the CGGA provided similar findings." (PMID 37301546, 2023).